CLDN4 (claudin 4)
Diseases named in the same sentence as CLDN4 in open-access papers (continued):
Sharing a sentence is not in itself a finding about the gene and the disease.
breast carcinoma (continued). "As a quality control of the ChIP samples, ChIP-qPCR confirmed the interaction of GRHL2 with the promoter region of CLDN4, a known direct target gene of GRHL2 in all three luminal, GRHL2-positive cell lines but not in the GRHL2-negative Hs578T human basal-B breast cancer cell line." (PMID 36691073, 2023). "Gene clusters correlating positively (including known GRHL2 targets such as ErbB3, CLDN4/7) or negatively (including TGFB1 and TGFBR2) with GRHL2 in the MCF7 knockout model, display similar correlation with GRHL2 in ER positive as well as ER negative breast cancer patients." (PMID 36691073, 2023).
gastric cancer (59 papers, 2005 to 2025). A primary or metastatic malignant neoplasm involving the stomach. "In contrast, high CLDN4 levels have been associated with enhanced barrier function and DNA hypomethylation in gastric cancer." (PMID 40687428, 2025). "The tight junction protein encoded by the CLDN4 gene has been associated with gastric cancer progression and reduced sensitivity to chemotherapy." (PMID 40724830, 2025). "For example, low claudin-4 expression is significantly associated with improved survival in intermediate-type growth pattern gastric carcinoma." (PMID 37627123, 2023). "Membranous claudin-4 expression is associated with gastric cancer progression and prognosis in gastric carcinoma." (PMID 36010553, 2022). "In contrast, our data showed that CLDN4 was overexpressed in H. pylori-associated differentiated type gastric cancer." (PMID 31040910, 2019). "A meta-analysis indicates that Claudin-4 over-expression is associated with progress of gastric cancer and poor survival in gastric cancer patients." (PMID 28376864, 2017). "This meta-analysis shows that over-expression of claudin-4 is associated with progress of gastric cancer and poor prognosis of gastric cancer patients." (PMID 26109060, 2015). "Seven studies with 1026 patients investigated the association between claudin-4 expression and the tumor stage of gastric cancer." (PMID 26109060, 2015). "In conclusion, this meta-analysis shows that over-expression of claudin-4 is associated with poor prognosis of gastric cancer patients and leads to progress of gastric cancer." (PMID 26109060, 2015). "Over-expression of claudin-4 was also associated with advanced stage (OR: 1.96, 95 % CI: 1.08–3.56) and lymphoid node metastasis (OR: 1.72, 95 % CI: 1.05–2.81) of gastric cancer patients." (PMID 26109060, 2015). "Overall, the pooled results showed that over-expression of claudin-4 was associated with a poor survival in gastric cancer patients (HR: 2.01, 95 % CI: 1.62–2.50)." (PMID 26109060, 2015). "The meta-analysis showed that over-expression of claudin-4 was associated with advanced stage of gastric cancer (OR: 1.96, 95 % CI: 1.08–3.56, P = 0.031), and moderate heterogeneity was found among the studies (I2 = 69.0, P = 0.004)." (PMID 26109060, 2015). "In the present study, pooled by the data from published studies, we found that over-expression of claudin-4 was associated with poor prognosis of gastric cancer, advanced clinical stage, and lymphoid node metastasis." (PMID 26109060, 2015). "The current reports on the association of claudin-4 expression with gastric cancer outcome were inconsistent." (PMID 26109060, 2015). "The present study showed that claudin-4 is overexpressed in human gastric cancer cells and associated with increased cell invasiveness." (PMID 25120725, 2014). "In this study, we aimed to identify the clinicopathological associations and prognostic value of claudin-4 expression in gastric cancer." (PMID 23822740, 2013). "In the present study, we found that decreased expression of claudin-4 was significantly associated with histological differentiation in gastric cancer." (PMID 23822740, 2013). "In gastric carcinoma, high levels of CLDN4 have been found to be significantly associated with MMP-9 expression, which in turn can degrade type IV collagen of ECM and facilitate cancer cell invasion." (PMID 23236365, 2012). "In addition, CLDN4 has been shown to be involved in epithelial–mesenchymal transformation (EMT) in gastric cancer and is the most important protein associated with lymphatic invasion and can be used as a prognostic marker." (PMID 34887379, 2021). "We observe that Claudin-4 is up-regulated in gastric cancer and is associated with poor prognosis." (PMID 28819095, 2017).
gastric cancer (continued). "Seven studies with 1030 patients investigated the prognostic value of claudin-4 on the gastric cancer patients, and the pooled results showed that over-expression of claudin-4 was associated with a poor survival in gastric cancer patients (HR: 2.01, 95 % CI: 1.62–2.50, P < 0.001)." (PMID 26109060, 2015). "Moreover, claudin-4 has been reported to be highly unregulated in gastric cancer, with an association between the up-regulation of claudin-4 and lymph node metastasis." (PMID 23919729, 2013). "In studies of gastric cancer, claudin-4 expression was found to be associated with bivalent histone modifications, and decreased inhibitory histone methylation as well as increased active histone methylation was associated with claudin-4 overexpression in gastric cancer cells." (PMID 36959784, 2023). "Compared with adjacent normal tissues or gastric epithelial cells, the expression of CLDN4 in gastric cancer tissues and cell lines is reduced." (PMID 41461671, 2025). "Histologically, CLDN4 expression is commonly higher in well-differentiated intestinal-type gastric cancers and is often lost in the poorly differentiated diffuse type." (PMID 40687428, 2025). "CLDN4 protein plays an important role in gastric cancer proliferation and metastasis: a meta-analysis found that high CLDN4 correlates with more advanced disease and poor prognosis." (PMID 40687428, 2025). "A recent study demonstrated the involvement of CLDN-4 in modulating cell proliferation and chemotherapeutic sensitivity in gastric cancer." (PMID 38338691, 2024). "According to the findings of Luo and colleagues, the expression of CLDN4 was much lower in gastric cancer tissues and cell lines when compared to nearby normal tissues or stomach epithelial cells." (PMID 37057131, 2023). "In gastric cancer, plasma membrane CLDN4 is overexpressed in well-differentiated carcinomas, whereas plasma membrane CLDN4 that forms a TJ with E-cadherin is decreased in poorly differentiated carcinomas, reflecting EMT phenotype." (PMID 36982569, 2023). "Knocking down CLDN4 in gastric cancer and bladder cancer results in a mild decrease in transepithelial electrical resistance (TER), an indicator of TJ function." (PMID 36982569, 2023). "In gastric cancer, CLDN4 was found to enhance the proliferation, invasion and epithelial-mesenchymal transition (EMT) of gastric cancer cells, and was reversed by miR-596 and miR-3620-3p." (PMID 35418179, 2022). "Epigenetic involvement has also been reported for CLDN4, wherein, similar to this study, CLDN4 overexpression by promoter hypomethylation was reported in gastric cancer." (PMID 35742959, 2022). "We aimed to investigate the differential expression of CLDN-4 in early gastric cancer (EGC) according to its clinicopathological characteristics." (PMID 35743616, 2022). "miR-3620 was able to reverse claudin-4 upregulation in gastric cancer cell lines, which is responsible for reinforcing proliferation, invasion, and epithelial–mesenchymal transition in gastric cancer and with poor prognosis." (PMID 35992881, 2022). "A recent study showed that claudin-4 reinforced proliferation, invasion, and epithelial–mesenchymal transition in gastric cancer cells." (PMID 34638619, 2021). "A meta-analysis confirmed the elevated protein levels of CLDN-4 in larger tumor size in gastric carcinoma." (PMID 33407452, 2021). "LncRNA KRTAP5‐AS1 and TUBB2A regulate CLDN4 expression by acting as a sponge to adsorb miR‐596 or miR‐3620‐3p in gastric cancer." (PMID 32364663, 2020). "In contrast, tight junction CLDN4 is plentiful in differentiated type gastric cancer to form anti-cancer drug barrier." (PMID 31040910, 2019). "These anti-tumoral findings were more pronounced MKN74 cell tumors, which showed higher expression of CLDN4 than did undifferentiated gastric cancer TMK-1 cells." (PMID 31040910, 2019). "In these differentiated/CDX2-positive gastric cancer cases, CLDN4 is at high levels than undifferentiated/CDX2-negative cases." (PMID 31040910, 2019).
gastric cancer (continued). "We investigated the effectiveness of anti-CLDN4 extracellular domain antibody 4D3 as a new molecular-targeted drug against gastric cancer using pathological specimens, as well as in vitro and in vivo experiments." (PMID 31040910, 2019). "DNA hypomethylation of the claudin-4 promotor is an important factor for its high expressions in gastric cancer." (PMID 31861759, 2019). "Of the three claudins we identified to interact with an HIF-1 network, CLDN1 and CLDN4 were previously reported as upregulated in gastric cancer progression, while CLDN18 was downregulated." (PMID 29050243, 2017). "Aberrant Claudin 4 expression plays an important role in the clinicopathological characteristics of gastric cancer." (PMID 28376864, 2017). "Claudin-4 has been shown to be strongly deregulated in gastric cancer (Reviewed in, Turksen and Troy 2011)." (PMID 26243458, 2016). "Although our meta-analysis was robust in identifying a correlation between claudin-4 over-expression and poor clinical outcome in gastric cancer, this study should be interpreted with caution in view of some limitations." (PMID 26109060, 2015). "From this family of proteins, claudin-4 is reported to be highly expressed in gastric intestinal-type adenocarcinoma and several previous studies have shown that claudin-4 is involved in gastric cancer." (PMID 24765156, 2014). "It was found that the expression of claudin-4 was significantly higher in gastric cancer cases with advanced depth of wall invasion, lymph node metastasis, lymphatic invasion and high tumor node metastasis stage." (PMID 25120725, 2014). "Immunohistochemistry was used to analyze the expression of claudin-4 in 329 clinical gastric cancer specimens and 44 normal stomach samples, 21 intestinal metaplasia samples, and 21 adjacent precursor lesions dysplasia samples." (PMID 23822740, 2013). "Our findings indicated that the five-year CSS rate for patients exhibiting high expression levels of claudin-4 in intermediate-type gastric cancer was 46.6%, which was similar to infiltrative-type gastric cancers (50.7%)." (PMID 23822740, 2013). "Further studies are warranted to elucidate the function of claudin-4 in the progression of gastric cancer." (PMID 23822740, 2013). "High expression of claudin-4 was observed in 69.7% of the expanding type and 72.8% of the intermediate type of gastric cancer, whereas only 36.6% of the infiltrative type exhibited high expression." (PMID 23822740, 2013). "Further stratified analysis demonstrated no significant prognostic difference between patients who exhibited high versus low expression of claudin-4 in expanding and infiltrative type gastric cancer." (PMID 23822740, 2013). "The relationship of claudin-4 expression with patient prognosis in gastric cancer is also controversial." (PMID 24009024, 2013). "Although our study comprises nearly the largest number of cases at present, the prognostic role of claudin-4 in gastric cancer remains ambiguous (P = 0.637)." (PMID 23822740, 2013). "The five-year cancer-specific survival rate for patients with low claudin-4 expression levels in intermediate-type gastric cancer was 76.4%, which was similar to all expanding-type gastric cancers (64.5%)." (PMID 23822740, 2013). "The findings in this study demonstrate claudin-4 aberrant expression in gastric cancer and precursor lesions." (PMID 23822740, 2013). "Of the gastric carcinoma samples investigated, 53.2% (175/329) of cases demonstrated high claudin-4 expression." (PMID 23822740, 2013). "In contrast, strong expression of claudin 4 significantly correlated with a decreased survival in gastric cancers." (PMID 19142187, 2009). "So far, claudin 4 has been the only TJ protein shown to be lost in correlation with poor gastric cancer differentiation." (PMID 19142187, 2009). "In gastric cancer, CLDN4 expression is elevated in Helicobacter pylori-positive cases." (PMID 36982569, 2023).
gastric cancer (continued). "Finally, we identified a gene set associated with the differentiation status of gastric cancer, including AGR3, CLDN3, CLDN4, FABP1, LGALS4, PHGR1, MYH14 and S100A14." (PMID 36729271, 2023). "CLDN4 is related to the tumor progression and malignancy of gastric cancer." (PMID 33006362, 2020). "In gastric cancer, the expression of CLDN4 is modulated by Helicobacter pylori." (PMID 32064037, 2020). "Anti-CLDN4 antibody has potential application as a new type of molecular targeted drug capable of enhancing the anti-cancer properties of existing drugs, and in the development of molecular targeted therapies against gastric cancer." (PMID 31040910, 2019). "The present study investigated whether the 4D3 antibody to the human CLDN4 extracellular domain (that we previously established) is capable of modulating chemotherapeutic sensitivity in gastric cancer (GC)." (PMID 31040910, 2019). "High CLDN4 expression in gastric cancer cases suggests that CLDN4 targeting by anti-CLDN4 antibody might be a relevant tool for treatment." (PMID 31040910, 2019). "Decreases in CLDN4 expression in undifferentiated/CDX2-negative gastric cancer might be explained as resulting from induction of the EMT phenotype." (PMID 31040910, 2019). "Claudin-4 is highly expressed in primary and metastatic prostate cancer and gastric cancer." (PMID 31861759, 2019). "Here the authors reveal a regulatory network in gastric cancer whereby claudin-4 expression is reduced by specific miRNAs, which are in turn bound by specific lncRNAs acting as competing endogenous RNAs (ceRNAs), resulting in increased claudin-4 expression." (PMID 28819095, 2017). "In this study, we discover a network regulating Claudin-4 in gastric cancer." (PMID 28819095, 2017). "The pooled hazard ratio (HR) with its 95 % confidence interval (95 %CI) was used to assess the prognostic value of claudin-4 expression with gastric cancer patients, and the pooled odds ratio (OR) with its 95 %CI was used to assess the association with clinical parameters." (PMID 26109060, 2015). "Currently, several studies have reported the relationship of claudin-4 expression and gastric cancer risk, but these results are not inconsistent." (PMID 26109060, 2015). "Overall, the results suggest that claudin-4 overexpression may promote gastric cancer metastasis through the increased invasion of gastric cancer cells." (PMID 25120725, 2014). "In addition, overexpression of claudin-4 in gastric cancer cells was shown to lead to increased expression of MMP-2 and -9, thus, suggesting a mechanism for the increased invasive potential of claudin-4-expressing gastric cancer cells." (PMID 25120725, 2014). "However, in intermediate type growth pattern gastric cancer, the prognosis for patients exhibiting low expression levels of claudin-4 was significantly better compared to those with high expression levels (P = 0.023)." (PMID 23822740, 2013). "The expression of claudin-4 could serve as a basis for identifying gastric cancer of the intermediate type." (PMID 23822740, 2013). "There have been previous reports to indicate that claudin-4 is upregulated in primary breast, ovarian, prostate squamous cell carcinoma and pancreatic cancers but is downregulated in gastric cancer." (PMID 18648369, 2008). "Thus, CLDN4 might play a role in integrin signaling, or in CD44 associated with stemness in undifferentiated/CDX2-negative gastric cancer." (PMID 31040910, 2019). "It is suggested that difference in duration of H. pylori infection might cause difference in effect: atrophic gastritis and initiation of gastric carcinogenesis with CLDN4 downregulation might precede differentiated type gastric cancer with CLDN4 overexpression." (PMID 31040910, 2019).
gastric cancer (continued). "Nevertheless, as the anti-tumoral mechanism of 4D3 is in effect irrespective of whether abrogation of tight junction occurs, or whether the CLDN4-ITGβ1 relationship is inhibited, higher expression of CLDN4 might be responsible for the higher anti-tumoral effect to gastric cancer." (PMID 31040910, 2019). "The expression of claudin-4 in gastric cancer was negatively associated with DNA methylation, and miRNA can lead to decreased expression of claudin-18 by binding to its 3'-UTR region and subsequently promote the proliferation, migration, and invasion of gastric cancer cells." (PMID 28350854, 2017). "Furthermore, the claudin-4-expressing gastric cancer cells were found to increase MMP-2 and MMP-9 expression, indicating that claudin-mediated increased cell invasion may be the result of MMP protein activation." (PMID 25120725, 2014). "The biological role of claudin-4 in gastric cancer remains unclear." (PMID 23822740, 2013). "Moreover, this study demonstrated that expression of claudin-4 could potentially be utilized as a basis to further identify gastric cancers of the intermediate type." (PMID 23822740, 2013). "Thus, the expression of claudin-4 could potentially be utilized as a basis to further identify gastric cancers of the intermediate type." (PMID 23822740, 2013). "Silencing CLDN4 increases the phosphorylation of PI3K and AKT, and increases the malignant progression of gastric cancer cells." (PMID 41461671, 2025). "In the sphere of gastric cancer (GC), KRTAP5-AS1 assumes a multifaceted role by acting as a ceRNA, thereby modulating the functionality of the Claudin-4 network (CLDN4)." (PMID 37814309, 2023). "LncRNA-KRTAP5-AS1 and lncRNA-TUBB2A can function as ceRNAs that bind miR-596 and miR-3620-3p and regulate Claudin-4 to promote the growth, metastasis, and epithelial-mesenchymal transition (EMT) of gastric cancer." (PMID 33937069, 2021). "Claudin-4 was observed to be overexpressed in GC, moreover, increased expression of CLDN4 results in enhanced invasion and migration of gastric cancer cells." (PMID 34822542, 2021). "The silencing of CLDN4 activates PI3K/AKT signaling pathway and potentiates the proliferation of gastric cancer cells." (PMID 33006362, 2020). "In our previous study, immunohistochemistry was used to examine the expression levels of claudin-4 and MMP-2 and -9 in 189 gastric cancer samples, and their correlation with tumor invasion and clinicopathological parameters was analyzed." (PMID 25120725, 2014). "Using immunohistochemical analysis, the present study showed that the expression of claudin-4 was found to correlate with tumor invasion and MMP-2 and -9 expression in gastric cancer." (PMID 25120725, 2014). "However, the prognostic significance of claudin-4 in gastric cancer remains unclear." (PMID 23822740, 2013). "Moreover, in gastric cancer, TSPEAR-AS2 promotes disease progression by upregulating CLDN4 via miR-1207-5p." (PMID 41008534, 2025). "Moreover, we have previously shown that CLDN4, as well as CLDN7, binds to integrin β1 and activates FAK in BUC in gastric cancer." (PMID 35742959, 2022). "LncRNA-KRTAP5-AS1 and lncRNA-TUBB2A could act as ceRNAs to affect the function of Claudin-4, which reinforces proliferation, invasion, and EMT in gastric cancer." (PMID 31761783, 2019). "Non-tight junction CLDN4 is plentiful in undifferentiated type gastric cancer to activated integrin β1, which increases stemness to provide metastability anti-apoptotic survival." (PMID 31040910, 2019). "Among the various claudin proteins related to gastric cancer, the function of claudin-4 was not consistent." (PMID 23822740, 2013). "Our group also showed that claudin-4 overexpression inhibits the migration and invasion of gastric cancer cells without affecting cell growth." (PMID 24009024, 2013).